TIPE2 (TNF alpha induced protein 8 like 2)
Description:
Acts as a negative regulator of innate and adaptive immunity by maintaining immune homeostasis. Plays a regulatory role in the Toll-like signaling pathway by determining the strength of LPS-induced signaling and gene expression. Inhibits TCR-mediated T-cell activation and negatively regulate T-cell function to prevent hyperresponsiveness (By similarity). Also inhibits autolysosome formation via negatively modulating MTOR activation by interacting with RAC1 and promoting the disassociation of the RAC1-MTOR complex. Plays an essential role in NK-cell biology by acting as a checkpoint and displaying an expression pattern correlating with NK-cell maturation process and by negatively regulating NK-cell maturation and antitumor immunity (By similarity). Mechanistically, suppresses IL-15-triggered mTOR activity in NK-cells (By similarity).
Synonyms: TNFAIP8L2; FLJ23467
Tractability: Small molecule: it has a binding pocket of medium quality. PROTAC: UniProt records ubiquitination sites on it; its protein half-life has been measured.
Gene: Protein-coding gene on chromosome 1 (151,156,621 to 151,160,255, forward strand). Ensembl gene ENSG00000163154.
Subcellular location: Cytoplasm; Nucleus; Lysosome
Subcellular location (Human Protein Atlas): Vesicles
Pathways (Reactome):
Metabolism: PI Metabolism
Gene Ontology:
Molecular function: protein binding
Biological process: negative regulation of inflammatory response; negative regulation of T cell activation; regulation of intracellular signal transduction; regulation of apoptotic process
Cellular component: cytoplasm; lysosome; nucleus
Genetic constraint (gnomAD): Loss-of-function variants: 2 observed, 7.6 expected, observed/expected ratio (o/e) 0.26, 90% interval 0.11 to 0.83. That is too few expected variants to judge how well the gene tolerates losing a copy. Missense variants: 216 observed, 252.74 expected, observed/expected ratio (o/e) 0.85, 90% interval 0.76 to 0.96. Synonymous variants: 91 observed, 105.65 expected, observed/expected ratio (o/e) 0.86, 90% interval 0.73 to 1.02.
Homologues: Orthologues: chimpanzee TNFAIP8L2 (99% identical), macaque TNFAIP8L2 (99% identical), guinea pig TNFAIP8L2 (97% identical), rabbit TNFAIP8L2 (96% identical), mouse Tnfaip8l2 (94% identical), dog TNFAIP8L2 (93% identical), pig TNFAIP8L2 (93% identical), rat Tnfaip8l2 (92% identical), tropical clawed frog tnfaip8l2 (64% identical), zebrafish tnfaip8l2b (62% identical), zebrafish tnfaip8l2a (60% identical), Drosophila melanogaster sigmar (40% identical). Paralogues in human: TIPE1 (58% identical), TIPE3 (55% identical), TNFAIP8 (54% identical).
Diseases named in the same sentence as TIPE2 in open-access papers:
TIPE2 is named in the same sentence as 118 diseases in open-access papers, as found by Europe PMC text mining. Sharing a sentence is not in itself a finding about the gene and the disease. The quoted sentences say what the papers report.
gastric cancer (16 papers, 2016 to 2025). A primary or metastatic malignant neoplasm involving the stomach. "This information implied that the effects of gracillin fighting against gastric cancer were also associated with TIPE2-mediation of mitochondrial apoptosis." (PMID 34630074, 2021). "TIPE2 is an inhibitor of gastric cancer cell growth, and might promote a p27-associated signaling cascade that leads to control the cell cycle and cell division, leading to the conclusion, that TIPE2 may regulate proliferation of gastric cells." (PMID 32599870, 2020). "In gastric cancer, overexpression of TIPE2 suppresses metastasis through advancing β-catenin degradation, and in cancer esophagus through blockage of the Wnt/β-catenin pathway." (PMID 40060230, 2025). "Among different cancer types, TIPE2 expression level was decreased in liver cancer, small cell lung cancer, stomach cancer, esophageal cancer and prostate cancer, and increased in kidney cancer, colon cancer and thyroid papillary carcinoma." (PMID 35388275, 2022). "TIPE2 overexpression inhibits gastric cancer metastasis by promoting β-catenin degradation and inhibiting β-catenin signaling pathway." (PMID 35388275, 2022). "In human cancer, TIPE2 is weakly expressed in hepatocellular carcinoma, small cell lung cancer, gastric cancer, breast cancer, esophageal cancer and oral tongue squamous cell carcinoma, which demonstrated that TIPE2 was involved in cancer progression." (PMID 34249724, 2021). "The results provided a theoretical basis for developing drugs to treat gastric cancer by targeting TIPE2." (PMID 34630074, 2021). "TIPE2 inhibits gastric cancer by regulating cell proliferation, apoptosis, and inflammation through inhibition of the PI3K/Akt and Ras-Raf-MEK-ERK1/2 signaling pathways." (PMID 34446024, 2021). "Of course, several issues regarding how gracillin regulates TIPE2 and the more precise mechanism of TIPE2 in gastric carcinoma remain obscure." (PMID 34630074, 2021). "In this study, we aimed to identify a potential TIPE2 candidate for restraining gastric carcinoma from a traditional natural herb, and to clarify the mechanism by which the candidate suppresses gastric carcinoma via TIPE2." (PMID 34630074, 2021). "For instance, overexpression of TIPE2 suppressed the growth of gastric cancer cells via reduction of Akt and ERK1/2." (PMID 31817720, 2019). "In human cancer, decreased expression of TIPE2 is observed in hepatic cancer, gastric cancer tissues and small cell lung cancer." (PMID 30586922, 2018). "TIPE2 has been demonstrated to promote the apoptosis by regulating caspase-9 and caspase-3 in both lung cancer and gastric cancer." (PMID 30534358, 2018). "Adenovirus-directed expression of TIPE2 suppresses gastric cancer growth by induction of apoptosis and inhibition of AKT and ERK1/2 signaling, suggesting that, similar to TIPE1, TIPE2 mostly inhibits various cancer cell growths by the induction of apoptosis." (PMID 30586922, 2018). "However, it’s seldomly reported that several medicinal agents or candidates targeted TIPE2 for treating diseases, including gastric cancer." (PMID 34630074, 2021). "TIPE2 protein was first identified only a few years ago, and since then a great deal of evidence has indicated that TIPE2 plays a crucial role in suppressing gastric cancer." (PMID 34630074, 2021). "Therefore, the development of a TIPE2 regulator that suppresses gastric cancer and clarifying its function would be encouraging for the clinical treatment of gastric cancer and is urgently needed." (PMID 34630074, 2021). "Interestingly, gracillin, a component from the ethyl acetate extraction of Rhizoma Paridis, was identified to induce the expression of TIPE2 and inhibit the cell proliferation in gastric cancer BGC-823 cells." (PMID 34630074, 2021). "Together, these results confirmed that gracillin could inhibit gastric cancer cell proliferation via AKT phosphorylation and cell cycle distribution, which may be associated with TIPE2 expression." (PMID 34630074, 2021).
gastric cancer (continued). "Therefore, exploring TIPE2’s mediator would be an important and significant strategy in the development of new anti-tumor medicine for gastric cancer." (PMID 34630074, 2021). "Several previous reports revealed that TIPE2 could inhibit the expression of bcl2 and suppress mitochondrial apoptosis as a tumor suppressor in gastric cancer cells and other tumor cells." (PMID 34630074, 2021). "This information demonstrates that TIPE2 could be a novel and extremely potent gastric cancer target that suppresses gastric cancer through mediating multiple molecular pathways in patients with gastric tumors." (PMID 34630074, 2021). "We identified gracillin as a TIPE2 inducer from Rhizoma Paridis and elucidated the potential mechanism by which gracillin alleviates gastric carcinoma via TIPE2-mediated inhibition of proliferation, induction of endogenous apoptosis, and suppression of migration." (PMID 34630074, 2021). "In addition, TIPE2 also suppressed the metastasis of gastric cancer cells through the activation of Glycogen synthase kinase 3 beta (GSK3β) and the inhibition of Akt." (PMID 31817720, 2019). "Moreover, adenovirus-mediated human TIPE2 gene transfer (AdVTIPE2) led to the suppression of gastric cancer cells’ growth through decreased Akt, ERK1/2, and activation of the intrinsic apoptotic pathway." (PMID 31817720, 2019). "TIPE2 inhibits proliferation of gastric cancer cells by up-regulating p27." (PMID 33817189, 2019). "Similarly, Wu and their group also showed that TIPE2 suppressed the metastasis of gastric cancer cells via Akt inhibition." (PMID 31817720, 2019). "The expression of TIPE2 could control these defects of gastric cancer cells." (PMID 34630074, 2021). "However, it has not been well reported that several medicinal agents could regulate TIPE2 to fight against diseases such as gastric cancer." (PMID 34630074, 2021). "It had been verified that TIPE2 could suppress cell growth and proliferation by inducing the inhibition of the AKT and ERK1/2 pathways and promoting the p27-associated signal cascade in gastric cancer cells." (PMID 34630074, 2021). "Furthermore, the overexpression of TIPE2 could suppress the proliferation and migration of gastric cancer BGC823 cells." (PMID 34630074, 2021). "However, candidates targeting TIPE2 to restrain gastric carcinoma are as yet seldom reported." (PMID 34630074, 2021). "Furthermore, we assessed the mechanism by which gracillin suppressed gastric carcinoma, and found that gracillin could induce cellular apoptosis and inhibit migration via TIPE2-mediated endogenous apoptosis and EMT pathway in BGC-823." (PMID 34630074, 2021). "The emerging evidence shows that TIPE2 could inhibit gastric carcinoma growth and metastasis." (PMID 34630074, 2021). "Our present data show that gracillin suppresses the migration of gastric cancer BGC-823 cells, and that TIPE2 partly participated in this effect." (PMID 34630074, 2021). "Adenovirus-mediated human TIPE2 overexpression significantly inhibited AGS and HGC-27 gastric cancer cell growth and induced AGS and HGC-27 tumor cell apoptosis in vitro." (PMID 32599870, 2020). "TIPE2 expression was lost in AGS, HGC-27, and SGC-7901 gastric cancer cells; gained-expression of TIPE2 suppresses cell migration and invasion in vitro via inhibiting protein kinase B (Akt)/GSK3β/β-catenin signaling." (PMID 33817189, 2019). "Decreased TIPE2 expression were previously reported in a number of tumors such as hepatocellular carcinoma (HCC), gastric cancer, glioma and prostate cancer." (PMID 30186591, 2018). "In contrast, TIPE2 expression is decreased or even absent in some specific tumors, including primary liver cancer 45, gastric cancer 46, glioma 47 and prostate cancer." (PMID 33850476, 2021).
gastric cancer (continued). "The present research started with screening active compounds for inhibiting the proliferation of gastric cancer cell BGC-823 and regulating TIPE2 protein expression from the fractions of four medicinal plants Curcuma longa L., Tripterygium Wilfordii, Rhizoma Paridis, and Reynoutria japonica Houtt." (PMID 34630074, 2021). "Biochemical molecular analysis revealed that TIPE2 could reduce the activation of RAC1 and MMP9 by binding to RAC1, thereby suppressing gastric cancer cell metastasis." (PMID 34630074, 2021). "Our previous research suggested that TIPE2 is missing or has low expression in gastric carcinoma but not in normal gastric mucosa." (PMID 34630074, 2021). "On one hand, TIPE2 expression is down-regulated in peripheral blood mononuclear cells (PBMCs) of patients with SLE and HBV or HCV-induced hepatitis, as well as gastric cancer, hepatocellular carcinoma and non-small cell lung cancer tissues." (PMID 28851386, 2017). "Also, TIPE2 is reported to elicit cell apoptosis by activating caspase three and caspase 9, inducing the cleavage of PARP, and inhibiting bcl-2 expression in BGC-823 gastric cancer cells." (PMID 34630074, 2021). "Furthermore, TIPE2 suppressed the epithelial-mesenchymal transition (EMT) and metastasis of tumor cells via suppressing PI3K/Akt and Wnt/β-catenin signaling pathways in some tumor types, including glioma, gastric cancer and breast cancer." (PMID 34249724, 2021). "It was shown that TIPE2 is reduced or absent in several tumors, including gastric cancer." (PMID 32599870, 2020). "TIPE2 expression is lower in tumor tissues of HCC and gastric cancer than that in adjacent non-tumor tissues, while on the contrary, its expression is higher in tumor tissue of colon cancer and renal cell carcinoma compared with that in normal tissues." (PMID 27556698, 2016).
hepatocellular carcinoma (13 papers, 2013 to 2026). A malignant tumor that arises from hepatocytes. "TIPE2 expression was lost or reduced in primary hepatocellular carcinoma (HCC) tissues and was significantly associated with tumor metastasis, cell growth, cell migration, and cell invasion." (PMID 33817189, 2019). "A recent study showed that TIPE2 can suppress the growth and aggressiveness of hepatocellular carcinoma cells through downregulation of the phosphoinositide 3-kinase/AKT signaling pathway." (PMID 31661000, 2019). "TIPE2 can inhibit activity of oncogenic Ras and therefore suppress cell survival and motility of hepatocellular carcinoma." (PMID 33817189, 2019). "Recently, TIPE2 is proved to be an endogenous inhibitor of Rac1 in liver by which it suppressed invasion and metastasis of hepatocellular carcinoma (HCC)." (PMID 25946186, 2015). "In present study, we provide evidence that TIPE2 inhibits effectively human hepatocellular carcinoma metastasis." (PMID 24274578, 2013). "In recent research, TIPE2 was thought as a tumor suppressor in hepatocellular carcinoma." (PMID 25946186, 2015). "It has been demonstrated that Rac1 is a key molecule in regulating the invasiveness of PTC, and our previous research found that TIPE2 functions through inhibiting Rac1 in hepatocellular carcinoma (HCC) and non-small cell lung cancer (NSCLC)." (PMID 30186591, 2018). "Moreover, our previous researches indicated that TIPE2 could inhibit Rac1 activation in innate immune cells and in human hepatocellular carcinoma (HCC)." (PMID 27556698, 2016). "Similarly, lower level of TIPE2 was observed in the hepatoma cell lines such as Huh7 and HepG2 cells compared to non-cancer Changliver cells (data not shown)." (PMID 27696294, 2016). "In addition, TIPE2 inhibited invasiveness and tumor development via reducing MMP9 expression by targeting Rac1 in hepatocellular carcinoma (HCC) and gastrointestinal stromal tumor." (PMID 34249724, 2021). "Besides, TIPE2 suppressed TNF-α-mediated metastasis of hepatocellular carcinoma (HCC) cells by inhibiting nuclear factor kappa B (NF-κB) and Erk1/2, indicating TIPE2 as a plausible target against HCC metastasis." (PMID 31817720, 2019).
systemic lupus erythematosus (10 papers, 2016 to 2025). An autoimmune multi-organ disease typically associated with vasculopathy and autoantibody production. "TIPE2 deficiency in mice leads to fetal inflammatory diseases, and abnormal expression of TIPE2 in humans was found to be associated with infectious diseases and autoimmune disorders, such as hepatitis B, systemic lupus erythematosus, asthma, and experimental stroke." (PMID 29042627, 2017). "It has been demonstrated that the TIPE2 level is reduced in the PBMCs of patients with systemic lupus erythematosus (SLE), and collagen-induced arthritis (CIA) mice with a negative correlation with the development of arthritis." (PMID 33815396, 2021). "The aberrant expression of TIPE2 was found in PBMCs of patients with systemic lupus erythematosus (SLE) or chronic hepatitis B and asthmatic children 15-17." (PMID 33850476, 2021). "In fact, TIPE2 down-regulation was found in the peripheral blood mononuclear cells from patients with Systemic Lupus Erythematosus (SLE)." (PMID 31616442, 2019). "Moreover, TIPE2 was found to be abnormally expressed in peripheral blood mononuclear cells (PBMCs) from patients with chronic hepatitis B or systemic lupus erythematosus (SLE) and from asthmatic children." (PMID 28626770, 2017). "TIPE2 expression was downregulated in peripheral blood mononuclear cells from patients with systemic lupus erythematosus, which indicates that the miR-21-TIPE2 axis may play important roles during the pathogenesis of SLE." (PMID 27271606, 2016). "In systemic lupus erythematosus (SLE), AAV-mediated expression of TNF-α-inducible protein 8-like 2 (TIPE2) reprograms macrophage polarization toward the M2 phenotype, restoring immune homeostasis and mitigating SLE severity." (PMID 40284659, 2025). "In addition to inflammatory diseases, TIPE2 is also an essential regulator in the pathogenesis of autoimmune diseases, such as systemic lupus erythematosus (SLE) and diabetic nephropathy (DN)." (PMID 27029075, 2016).